IL7R (interleukin 7 receptor)
Diseases named in the same sentence as IL7R in open-access papers (continued):
Sharing a sentence is not in itself a finding about the gene and the disease.
asthma (27 papers, 2009 to 2026). "ADAM19 and IL-7R were also associated with asthma outcomes in the FinnGen database when the same variants identified in the primary analysis were used as exposure factors." (PMID 39806440, 2025). "The association of IL-7Rα gene polymorphisms with asthma has been observed in different populations." (PMID 29670037, 2018). "In this study, we report an analysis of association between single nucleotide polymorphisms (SNPs) in TSLP, OX40L, IL7R, and RXRα and AR in three independent studies of children with asthma from Costa Rica, North America, and Sweden." (PMID 21244681, 2011). "Additionally, using the same analysis method in the FinnGen database, we found that IL1-R1, ADAM19, and IL7R were associated with asthma risk, further demonstrating the stability of the results obtained in this study." (PMID 39806440, 2025). "Exon 4 of IL-7Rα single-nucleotide polymorphism (SNP) is correlated with the severity of asthma." (PMID 29670037, 2018). "We genotyped 15 single nucleotide polymorphisms (SNPs) in TSLP, OX40L, IL7R, and RXRα in three independent cohorts: 592 asthmatic Costa Rican children and their parents, 422 nuclear families of North American children with asthma, and 239 Swedish children with asthma." (PMID 21244681, 2011). "For example, APOE ε4 cannot be intervened as a genetic marker, while the inflammatory pathways of asthma (such as IL‐7R signaling) can be targeted through drugs (such as anti‐IL‐7R antibodies) or lifestyle adjustments." (PMID 40951943, 2025). "Another asthma‐specific target is IL‐7R, which acts as a receptor for interleukin‐7 (IL‐7) and TSLP." (PMID 37186423, 2023). "More recently, in vivo studies have demonstrated that DEHP induces Th2 and Th17 immune responses and airway inflammation in mice, and thymic stromal lymphopoietin (TSLP), Th2 immune response and interleukin-7 receptor in rats; all of which exacerbates asthma." (PMID 31368075, 2019). "Of the upregulated genes, NTS, TLR1, and MPO mRNA was only detectable in the asthma samples, whilst of the downregulated genes, IL7R and PDE4R mRNA were only observed in the control samples." (PMID 31221987, 2019). "Identifying and clarifying the regulation of TSLPR and IL-7Rα in pediatric asthma are still difficult, because the type of blood cell and the expression for each blood cell in different stages of atopic diseases are poorly understood." (PMID 29670037, 2018). "Therefore, isotype or anti-IL-7Rα antibodies were administered late in pregnancy to mothers with asthma to transiently remove fetal lung ILC2s." (PMID 39805834, 2025). "Integrated single‐cell RNA sequencing analysis of asthma PBMCs and AD CSF revealed IL7R may utilize the MIF‐CD74‐CXCR4 pathway to complete crosstalk between CD4 T cells and macrophages and contribute to AD disease development." (PMID 40951943, 2025). "Preclinical studies have indicated that OSE-127, a drug targeting IL7R, is effective for asthma." (PMID 37809092, 2023). "Furthermore, increased receptor complexes form of TSLPR and IL-7R in airway epithelial cells asthma group hasn’t been blocked in sTSLP treatment group." (PMID 35351157, 2022). "However, clarifying and identifying the regulation of TSLPR and IL-7Rα in pediatric asthma is still difficult because the type of blood cells and the type of expression for each blood cell in different stages of atopic diseases are poorly understood." (PMID 29670037, 2018). "Finally, IL-7R, a candidate gene from ECA21, directly interacts with FOXP3 which is a regulatory T-cell transcription factor implicated in the pathophysiology of human asthma." (PMID 21843342, 2011). "SNPs in OX40L, IL7R, and RXRα were not consistently associated with AR in children with asthma." (PMID 21244681, 2011). "IL7R, a component of the TSLP receptor, as well as ICOS and IL2RA, genes important in type 2 inflammatory responses, were increased in females with asthma compared to males with asthma." (PMID 41508394, 2026).
asthma (continued). "In Asthma 3, JUN is also repressed while the expression patterns of IL7R, IL32, and CCL5 are more similar to healthy controls." (PMID 41550933, 2025). "A causal relationship exists between genetically determined protein levels of IL1R1, IL7R, ECM1, CD200R1, ADAM19, IL-6 sRa, and Layilin (LAYN) and asthma." (PMID 39806440, 2025). "Our study demonstrated a causal relationship between genetic determinants, including IL1R1, IL7R, ECM1, CD200R1, ADAM19, IL-6 sRa, and Layilin (LAYN) protein levels, and asthma." (PMID 39806440, 2025). "Further studies are required to identify the roles of TGF‐β1, IL‐7R, and TLR‐3 in asthma management." (PMID 39575691, 2024). "Eight protein-disease pairs were ranked as the most valuable findings after the filtering, which include IL-7R and TNFSF12 level on asthma; ACE level on COPD; AIF1 level on HF; SERPINF1 level on stroke; and SERPINE2, F11, KLKB1, and ABO level on VTE." (PMID 36388766, 2022). "Currently, there are no studies on combined therapy targeting IL1-R1 and IL-7R, providing new insights for our research on targeted asthma medications." (PMID 39806440, 2025). "We confirmed the asthma in the OVA/Alum model mice was not alleviated by the anti-IL-7Rα treatment from another experiment using non-pregnant female mice." (PMID 39805834, 2025). "SMR results suggested that therapies targeting FPR1, IL1RAP, IL7R, and IL18RAP inflammatory variables may be able to prevent an increase in AD in moderate to severe asthma." (PMID 40951943, 2025). "Among them, thymic stromal lymphopoietin (TSLP) is a novel interleukin (IL)-7-like cytokine and could initiate type 2 inflammatory response by TSLPR heterocomplex, which is composed of the IL-7Rα chain and TSLPR chain, in asthma airway." (PMID 35351157, 2022). "ILC2s are characterized by the absence of known lineage markers and antigen receptors as well as the expression of surface markers CD45, CD25 (IL-2Rα), CD127 (IL-7Rα), and ST2 (IL-33R) in human asthma as well as in rodent models of respiratory allergic inflammation." (PMID 31231357, 2019). "Among these targets, FPR1 (Formyl Peptide Receptor 1), IL1RAP (Interleukin 1 Receptor Accessory Protein), IL7R (Interleukin 7 Receptor), and IL18RAP (Interleukin 18 Receptor Accessory Protein) warrant additional exploration as potential therapeutic targets for AD and moderate to severe asthma." (PMID 40951943, 2025). "Therefore, RBP-jCKO;IL7rα-/- animals provide a suitable system in which to determine if skin-barrier defects and AD-like skin inflammation including a systemic Th2 response with its consequences (e.g., elevated IgE) could confer susceptibility to asthma in the absence of TSLP signaling." (PMID 19557146, 2009).
acute lymphoblastic leukemia (23 papers, 2009 to 2025). Leukemia with an acute onset, characterized by the presence of lymphoblasts in the bone marrow and the peripheral blood. "In childhood B‐cell precursor acute lymphoblastic leukaemia, IL7R has been reported to be associated with infiltration and relapse of central nervous system." (PMID 36802116, 2023). "More recently, the finding of multiple and diverse activating IL7Rα mutations in acute lymphoblastic leukemia has created a unique opportunity to further study the functioning of this receptor." (PMID 31817502, 2019). "Gain-of-function mutations as well as insertions and deletions in the IL-7Rα gene frequently occur in both B and T cell acute lymphocyte leukemias (ALL)." (PMID 28484723, 2017). "Recent studies of acute lymphoblastic leukemia have identified activating mutations in components of the interleukin-7 receptor complex (IL7R, JAK1, and JAK3)." (PMID 26208852, 2015). "Whether acute lymphoblastic leukemia (ALL)-related IL7R gain-of-function mutations can trigger leukemogenesis remains unclear." (PMID 34907175, 2021). "A recent report that targeting BET proteins in high-risk acute lymphoblastic leukemia inhibits Myc and Il7r expression, both of which exhibit increased transcription in response to BCR in our experiment, also suggests Myc plays an important role during early phases of B cell activation." (PMID 25987903, 2015). "For example, a suite of mutations that increase the flux through the IL-7R/JAK1/JAK3/STAT5 pathway have been reported in acute lymphoblastic leukemia (ALL)." (PMID 38254802, 2024). "IL7R activation is well documented in hematological malignancies such as acute lymphoblastic leukemia, where it drives pro-survival and proliferation pathways (notably via JAK/STAT, MAPK/ERK, and PI3K/AKT/mTOR signaling)." (PMID 41249788, 2025). "Since the IL-7R dimer with constitutive signaling came from lymphoblastic leukemias, the utilization of the structure like IL-7R dimer should be cautious." (PMID 38643203, 2024). "IL7R is reported to be relevant to prognosis in solid tumor and acute lymphoblastic leukemia." (PMID 35874754, 2022). "In vitro studies have shown that the IL7R in t-line acute lymphoblastic leukemia (T-ALL) mediates T-ALL cell proliferation and survival after binding to IL7 secreted by bone marrow and thymic stromal cells." (PMID 37381714, 2023). "Over 70% blasts with T-cell acute lymphoblastic leukemia (T-ALL) patients showed IL-7R-positive expression." (PMID 34497605, 2021). "The IL-7Rα targeted monoclonal antibody, lusvertikimab, has shown preliminary efficacy against ulcerative colitis and IL7Rα+ T cell acute lymphoblastic leukemia (T-ALL)." (PMID 41282927, 2025). "In hematologic malignancies such as T-cell acute lymphoblastic leukemia (T-ALL), pharmacological inhibition of the JAK-STAT pathway induces cell death in mutant cells that express IL-7Rα." (PMID 41360767, 2025).
diabetes (21 papers, 2013 to 2025). "Expression analysis of diabetes-associated DEGs such as CXCL8, IL7R, and NR4A1 showed significant alterations after 20(R)-Rg3 treatment." (PMID 41373625, 2025). "IL7R expression was reduced, and patients with lower expression of CD127 had longer diabetes-free intervals." (PMID 39137044, 2024). "Monoclonal antibodies (MAb) that antagonize the IL-7Rα are in investigation for treatment of a range of autoimmune diseases and inflammatory conditions, including diabetes, multiple sclerosis, rheumatoid arthritis, and inflammatory bowel disease." (PMID 31507594, 2019). "In this paper, we showed forced expression of IL-7R in OT-I T cells by a transgene enhanced CD8 T cell mediated diabetes in the RIP-mOVA model." (PMID 29272267, 2017). "In the group that received rat IgG, mice started to become hyperglycemic at 12 weeks of age, whereas the mice treated with anti-IL-7Rα mAbs showed a significant delay in diabetes onset." (PMID 28356069, 2017). "We and others previously demonstrated that sustained, long-term treatment (14 weeks) of NOD mice with anti-IL-7Rα monoclonal antibodies (mAbs) robustly prevented diabetes incidence." (PMID 28356069, 2017). "Disease remission was complete and durable, after a 4-week cycle of anti-IL-7Rα antibody starting at the time of diabetes onset." (PMID 26983628, 2016). "In the first report [47••], the selective inhibition of the IL-7Rα using a monoclonal antibody was able to prevent diabetes after only 2–3 injections starting at week 9 of age." (PMID 26983628, 2016). "In these studies, administration of IL-7R blocking antibodies once or twice a week prevented the onset of the disease and normalized blood glucose levels in 50–85% of mice after diabetes onset." (PMID 23970924, 2013). "Furthermore, through blocking the receptor IL-7R, we were able not only to prevent, but also reverse, the onset of diabetes in mice." (PMID 33003647, 2020). "Here, we asked whether a reduced duration of the treatment with anti-IL-7Rα antibodies retained efficacy in preventing diabetes." (PMID 28356069, 2017). "Two reports showed how IL-7Rα blockade was effective to prevent and revert diabetes." (PMID 26983628, 2016). "Tem cells from anti-IL-7Rα-treated mice were also adoptively transferred in recipient mice without causing diabetes and demonstrating that IL-7-signaling deprivation was related to a state of cell intrinsic tolerance." (PMID 26983628, 2016). "Since IL-7R Tg OT-I T cells showed only a modest improvement in long term survival, we investigated whether enhanced effector function could explain their significantly higher efficiency in inducing diabetes in RIP-mOVA mice." (PMID 29272267, 2017). "The same monoclonal antibody raised against the IL-7Rα was also tested on BALB/c mice receiving C57BL/6 islets under the kidney capsule, as model of islet transplantation in streptozotocin-induced diabetes [49•]." (PMID 26983628, 2016). "On the contrary, the same number of IL-7R Tg OT-I cells failed to induce diabetes in w.t. mOVA mice." (PMID 29272267, 2017). "Moreover, IL-7 accelerates diabetes in NOD mice, while blockade of the IL-7R can reverse diabetes in the same model." (PMID 23970924, 2013). "Although IL-7R Tg did not change PD1 expression on activated OT-I cells in vivo, the transgene enabled a significantly lower number of OT-I T cells to induce diabetes in the absence of PDL-1." (PMID 29272267, 2017).
HIV-1 infection (21 papers, 2010 to 2025). The type species of lentivirus and the etiologic agent of acquired immunodeficiency syndrome (AIDS). "Plasma IL-7 levels are elevated in untreated HIV-1 infection and subsequently restored along with IL-7Rα expression on αβ T cells during ART50." (PMID 39149467, 2024). "- Memory CD4+ T cells which mostly express the IL-7 receptor (IL-7R) α chain, CD127 are profoundly depleted during untreated HIV-1 infection." (PMID 31507594, 2019). "Dysregulated IL-7/IL-7R signaling in HIV-1 infection has been proposed by several groups as a critical link between HIV-1-driven immune activation and bystander CD4+ T cell loss." (PMID 31507594, 2019). "The top downregulated transcripts in cells from treated individuals were the transcription factor ZNF90; NHSL2, which has unknown function; and IL7R, which has been shown to play a role in CD4 T cell loss during HIV-1 infection." (PMID 36175869, 2022). "- HIV-1 infection disrupts IL-7/IL-7R signaling and CD4+ T cell memory formation." (PMID 31507594, 2019). "Untreated HIV-1 infection is characterized by a progressive depletion of memory CD4+ T cells which mostly express CD127, the α chain of the IL-7 receptor (IL-7R)." (PMID 31507594, 2019). "In addition, the high expression of IKZF2 and low level of interleukin-7 receptor (IL7R) are identifiable transcriptional spectra demonstrated in CD16 + CD8 T cells, which are related to chronic untreated HIV-1 infection." (PMID 34950704, 2021). "As IL-7Rα signaling in CD4+ T cells may affect TFH cell function and is adversely affected by HIV-1 infection, we have examined the relationship of IL-7Rα expression on ICOS+ cTFH cells with PcP-specific IgG2 antibody responses." (PMID 31068934, 2019). "We observed a similar downregulation of ZNF90 and IL7R when we compared ART to seronegative cells as when we compared untreated HIV cells were compared to seronegative, indicating these transcripts are changed in T cells during untreated or treated HIV-1 infection." (PMID 36175869, 2022).
melanoma (21 papers, 2011 to 2025). A malignant, usually aggressive tumor composed of atypical, neoplastic melanocytes. "A tetrad of IL2RA, IL2RG, IFNG, and IL7R genes were determined as hub genes and verified by qRT‐PCR, which were significantly associated with unfavorable prognosis in melanoma." (PMID 34159752, 2021). "Based on our observations, we hypothesized that high IL-7R expression may be associated with improved melanoma survival and durable response to therapy." (PMID 37459511, 2023). "Overexpressed IL2RA, IL2RG, IFNG, and IL7R were identified as the hub genes associated with melanoma metastasis, and may promote melanoma progression through activation of JAK—STAT signaling pathway." (PMID 34159752, 2021). "Several studies have demonstrated that elevated levels of IL2RG as well as genes such as IL2RA, IL7R and IFNγ can promote melanoma metastasis by increasing intratumoral regulatory T cells through activation of the JAK-STAT signaling pathway." (PMID 40096084, 2025). "Intratumoral IL7R is a positive prognostic for survival in metastatic melanoma, and in a melanoma model an IL7R-high CD8+ T cell population with central memory-like features and lack of exhaustion markers demonstrated superior antitumor activity." (PMID 40239619, 2025). "To investigate these findings further, we evaluated IL-7R expression by immunohistochemistry in a cohort of 60 patients with melanoma treated with checkpoint inhibitors at Yale." (PMID 37459511, 2023). "We revealed that IL-7R is an independent prognostic factor of survival in melanoma and other malignancies." (PMID 37459511, 2023). "To determine the relevance of these findings in human melanoma, we analyzed the pattern of IL-7R expression in the TME of a large cohort of melanoma patients." (PMID 37459511, 2023). "We next performed Cox-proportional hazard analysis of IL-7R expression in relation to overall survival in the melanoma cohort." (PMID 37459511, 2023). "We identify that IL-7R expression in human melanoma is an independent prognostic factor of improved survival." (PMID 37459511, 2023). "Our results identify a CD8+ population selectively marked by IL-7R expression that drives antitumor memory and can be used as a potent therapy for melanoma." (PMID 37459511, 2023). "Our study revealed that IL2RA、IL2RG, IFNG, and IL7R were hub genes in melanoma metastasis and involved in JAK—STAT signaling pathway that was identified as an central signaling pathway in metastatic melanoma, which was rarely illustrated in previous studies." (PMID 34159752, 2021). "We next stratified the melanoma cohort based on IL-7R expression into an IL-7Rhi and IL-7Rlo group." (PMID 37459511, 2023). "IL2RA, IL2R, IFNG, and IL7R were also significantly upregulated in melanoma tissues relative to normal tissues, and had a critically positive correlation to unfavorable prognosis in melanoma." (PMID 34159752, 2021). "Indeed, the blocking of IL‐7R, in a mice model of melanoma, suppressed tumor growth by modifying immune infiltrate suggesting that IL‐7/IL‐7R axis could be an interesting target for therapy." (PMID 36054746, 2022). "Like melanoma, MANA-specific TIL in NSCLC showed higher expression of CXCL13 and ENTPD1, and lower expression of IL7R compared with virus-specific TIL." (PMID 39900903, 2025). "And regulatory T‐cell proportion was indeed critically elevated in metastatic melanoma relative to primary melanoma, as well as in highly expressed IL2RA, IL2RG, IL7R, and IFNG group than their respective counterparts." (PMID 34159752, 2021). "Another relevant finding in this study was that overexpressed Treg cells in metastatic melanoma as compared with that in primary melanoma, were the pivotal intermediate components by which IL2RA, IL2RG, IL7R, and IFNG exert their immunosuppressive effect." (PMID 34159752, 2021).